CTNS (cystinosin, lysosomal cystine transporter)
Diseases named in the same sentence as CTNS in open-access papers (continued):
Sharing a sentence is not in itself a finding about the gene and the disease.
cystinosis (continued). "Nephropathic cystinosis is a lysosomal storage disorder caused by mutations in the CTNS gene encoding cystine transporter cystinosin that results in accumulation of amino acid cystine in the lysosomes throughout the body and especially affects kidneys." (PMID 25811383, 2015). "Approximately 95% of patients have severe bi-allelic mutations/deletions of CTNS, causing the most severe form of the disease, termed “nephropathic cystinosis” (OMIM 219800)." (PMID 25947233, 2015). "Cystinosis is a rare disorder caused by homozygous mutations of the CTNS gene on the short arm of chromosome 17q, encoding a ubiquitous cystine-selective transport channel in the lysosomal membrane." (PMID 22912749, 2012). "Cystinosis is a rare disease caused by homozygous mutations of the CTNS gene, encoding a cystine efflux channel in the lysosomal membrane." (PMID 22912749, 2012). "ATP6V0A1 was significantly downregulated in cystinosis and highly co-regulated with loss of CTNS." (PMID 40111391, 2025). "The reason for the lysosomal cystine accumulation was unknown until the 1980s when it was found that the lysosomal transporter for cystine (CTNS) is mutated in cystinosis leading to an increase of cystine in lysosomes about 100-fold above normal." (PMID 40546328, 2025). "Loss-of-function mutations in CTNS cause a lysosomal storage disease known as cystinosis." (PMID 40661466, 2025). "These phenotypes mirror cystinosis, the lysosomal storage disease caused by CTNS loss-of-function." (PMID 40661466, 2025). "We thus hypothesize that human JIP4 loss-of-function mutations may impair CTNS regulation and predispose patients to cystinosis-like phenotypes, even in the presence of an intact CTNS gene." (PMID 40661466, 2025). "In nephropathic cystinosis, the kidney is particularly affected, as CTNS deficiency induces proximal tubule dysfunction (Fanconi syndrome) and eventual end-stage renal failure, leading most cystinosis patients to eventually require renal transplantation for survival." (PMID 40661466, 2025). "Cystinosis is a rare hereditary disorder resulting from variants in the CTNS gene." (PMID 41480351, 2025). "Cystinosis is an inherited genetic mutation in the lysosomal transporter carrier protein (CTNS)." (PMID 39055402, 2024). "Cystinosis can also be confirmed by genetic assays identifying variants in the CTNS gene." (PMID 39113682, 2024). "Cystinosis is caused by mutations in the CTNS gene that codes for the protein cystinosin." (PMID 38380220, 2024). "Cystinosis is a rare, devastating hereditary disease secondary to recessive CTNS gene mutations." (PMID 36768921, 2023). "A recent study has raised the possibility that patients with cystinosis carrying nonsense CTNS mutations, such as the w138x mutation often found in French Canadians, could be treated with drugs that stimulate translational readthrough." (PMID 37111358, 2023). "Mutations in CTNS, the lysosomal cystine-proton symporter, cause cystinosis." (PMID 35977944, 2022). "The ocular cystinosis is associated with different mutations in CTNS gene." (PMID 35524314, 2022). "According to these data, we can assume that high cystine levels may correlate directly with the severity of cystinosis and may be an unfavorable prognostic factor for patients with LoF mutations in the CTNS gene." (PMID 35571017, 2022). "Cystinosis is a rare autosomal metabolic disorder caused by bi-allelic mutations in the CTNS gene." (PMID 34944047, 2021). "Mutations in CTNS are responsible for cystinosis, an autosomal recessive lysosomal storage disease." (PMID 34440723, 2021). "Cystinosis is a rare, incurable, autosomal recessive disease caused by mutations in the CTNS gene." (PMID 34502306, 2021). "Mutations or deletions in the ubiquitous gene CTNS cause cystinosis." (PMID 34943781, 2021). "Each form of cystinosis shows different mutations in the CTNS gene." (PMID 33171856, 2020).
cystinosis (continued). "Nephropathic cystinosis is a rare autosomal recessive lysosomal storage disease caused by the lysosomal accumulation of cystine because of mutations in the CTNS gene encoding cystinosin, a 367 amino acids lysosomal cystine transporter with seven transmembrane domains." (PMID 32354056, 2020). "Depending on the severity of mutations affecting the CTNS gene, there is three major clinical presentations of the cystinosis disease: the infantile nephropathic form (MIM: 219800), the juvenile nephropathic form (MIM: 219900), and the ocular non-nephropathic form (MIM: 219750)." (PMID 33308164, 2020). "Cystinosis is a rare disorder caused by recessive mutations of the CTNS gene." (PMID 31800572, 2019). "Nephropathic cystinosis is a type of unusual autosomal recessive LSD which is caused by mutations in the CTNS gene (encodes a lysosomal cystine transporter, cystinosin); the treatment of cystinosis are currently based on the drug called cysteamine which reduces the cystine level." (PMID 30717078, 2019). "Cystinosis is an autosomal recessive lysosomal storage disorder characterized by accumulation of cystine within all organs as a result of mutations in the CTNS gene (MIM 606272; GenBank NM_004937.2 17p13), which encodes the lysosomal cystine transporter cystinosin." (PMID 31672123, 2019). "Interestingly, in Asia population, very few cystinosis patients and CTNS mutations have been reported." (PMID 25866837, 2015). "Interestingly, in Asia population, limited cases with cystinosis were diagnosed and limited CTNS mutations were reported." (PMID 25866837, 2015). "This possibility was demonstrated recently in an in vitro study where MSCs were modified to express cystinosin, the gene for which (CTNS) is mutated in a rare disorder called cystinosis, which causes a large accumulation of cysteine in cells and eventually results in cellular apoptosis." (PMID 23786652, 2013). "While cystinosis is classically attributed to inactivating mutations in CTNS, our data raise the possibility that defects in CTNS regulation, such as impaired JIP4 function, could similarly disrupt cystine export and contribute to mismanagement of cysteine in disease." (PMID 40661466, 2025). "Because cystinosis is an autosomal recessive disorder, requiring the inheritance of 2 variants in the CTNS gene, individuals with cystinosis and their partners, especially consanguineous couples, could be offered genetic testing if it has not been previously completed." (PMID 38344731, 2024). "Further, at the functional level, we performed HPLC-MS/MS and showed a significant increase in cystine accumulation in CTNS-/- RPTECs, similar to intracellular cystine accumulation found in cystinosis patients (5–6 nmol/mg protein)." (PMID 40111391, 2025). "Research on cystinosis has predominantly focused on the renal phenotype, utilizing engineered kidney cell lines, patient‐derived kidney cells and CTNS knockout animal models." (PMID 41208577, 2025). "Cystinosis is a rare, autosomal, recessive, lysosomal-storage disease caused by mutations in the CYSTINOSIN (CTNS) gene, encoding cystine transporter." (PMID 41302105, 2025). "Cystinosis is a systemic lysosomal storage disease resulting from a defective CTNS gene, leading to the accumulation of cystine in all organs." (PMID 39990449, 2025). "We acknowledge that additional studies needed to understand the interplay between transcriptional regulations of ATP6V0A1 in cystinosis and if CTNS-/- cells, chronically treated with cysteamine, acquire any further changes to ATP6V0A1 expression." (PMID 40111391, 2025). "In 2023, Elena Levtchenko's group (Leuven, Belgium) transfected both mutant renal proximal tubular cells and podocytes from a cystinosis patient with a stabilized HA-tagged CTNS mRNA designed by RiboPro B.V. in the Netherlands." (PMID 40469087, 2025).
cystinosis (continued). "In cystinosis, sEVs loaded with the transporter protein CTNS have been shown to reduce pathologic cystine accumulation in co-cultured CTNS mutant fibroblasts or proximal tubular cells from cystinosis patients." (PMID 39860010, 2025). "Studies have detected increased autophagy in the urine of cystinosis patients and in RTECs of CTNS knockout mice, suggesting a role for autophagy in promoting apoptosis." (PMID 39723243, 2024). "Cystinosis is a rare lysosomal storage disease due to defective CTNS gene, encoding for CYSTINOSIN, a proton-driven lysosomal membrane cystine exporter." (PMID 37828038, 2023). "We studied the potential of CTNS mRNA therapy to ameliorate cystinosis, a monogenic lysosomal storage disorder having a well-defined phenotype, presenting with cystine accumulation and both podocyte and proximal tubular dysfunction in the kidney." (PMID 38016974, 2023). "First, we validated the LV constructs (LV_CTNS-3HA) in cystinosis fibroblasts, confirming CTNS protein expression via immunofluorescent staining and Western blot analysis." (PMID 35406807, 2022). "Nephropathic cystinosis (NC) (OMIM 219800; 219900) is a rare, autosomal recessive lysosomal storage disease caused by mutations in the CTNS gene that is estimated to affect 1 of every 100 000–200 000 live births." (PMID 35028272, 2022). "Primary fibroblasts from a patient with cystinosis were then seeded on the biomaterials: cellular transfection, accumulation of cystine, and secretion of the recombinant CTNS were finally evaluated." (PMID 35260693, 2022). "In this study, we report on a child, born to consanguineous parents, with dual molecular diagnoses: autosomal recessive primary microcephaly-5 (MCPH5) and nephropathic cystinosis, due to homozygous pathogenic variants in the ASPM and CTNS genes, respectively." (PMID 36553645, 2022). "CTNS-RD-04 consists of CD34+ enriched HSPCs that underwent ex vivo transduction using the pCCL-CTNS that carries the full-sequence, human cystinosis gene (CTNS) cDNA." (PMID 34943781, 2021). "The addition of microvesicles and/or exosomes derived from both mesenchymal stem cells (MSCs) and transduced insect cells containing wildtype CTNS protein to fibroblasts from patients with cystinosis corrected the cystine levels." (PMID 33920837, 2021). "Analysis of CTNS gene transcript allowed to identify a large homozygous deletion in the patient with infantile nephropathic cystinosis." (PMID 31672123, 2019). "In patients with cystinosis, cystine (which is the oxidized dimer form of cysteine) accumulates continuously in the lysosome owing to the defective CTNS, resulting in the formation of cystine crystals in every cell in the body, leading to multi-organ damage." (PMID 30591971, 2019). "The discovery of the CTNS gene has provided the fundamental basis for various molecular groundwork in cystinosis." (PMID 30513914, 2018). "Molecular analysis of the CTNS gene is a powerful tool for early diagnosis and can be used for prenatal diagnosis of cystinosis." (PMID 28950840, 2017). "Similar pathways were observed when comparing the expression profiles of control and cystinotic cells from patients with nephropathic cystinosis (MIM 219800), an autosomal recessive lysosomal storage disorders resulting from loss-of-function CTNS mutations." (PMID 27142334, 2016). "Here, we identify a mechanism of impaired chaperone-mediated autophagy (CMA) in cystinosis, a LSD caused by defects in the cystine transporter cystinosin (CTNS) and characterized by cystine lysosomal accumulation." (PMID 25586965, 2015). "In the present work, we study autophagic pathways in cystinosis, a LSD caused by defects in the cystine transporter cystinosin (CTNS)." (PMID 25586965, 2015). "We found that surface binding of GST-RAP was reduced by ~30% (p<0.05) in CTNS KD HK-2 cells and by ~60% (p<0.01) in ciPTEC derived from a cystinosis patient as compared to control." (PMID 25811383, 2015).
cystinosis (continued). "Here we show that human mesenchymal stem cells, from amniotic fluid or bone marrow, reduce pathologic cystine accumulation in co-cultured CTNS mutant fibroblasts or proximal tubular cells from cystinosis patients." (PMID 22912749, 2012). "The target ciPTEC(−/−)GFP cells were from a cystinosis patient bearing the common homozygous 57 kb deletion of the CTNS gene." (PMID 22912749, 2012). "We then co-cultured amniotic mesenchymal stem cells (amMSC) with various proportions of mutant fibroblasts from a cystinosis patient with homozygous deletion of the CTNS gene containing high intracellular levels of cystine." (PMID 22912749, 2012). "For example, SIV-infected genome contains upregulated aldehyde dehydrogenase 5 family member A1 (ALDH5A1, ID: H06676); and concurrent down regulated succinate dehydrogenase complex, subunit D (SDHD, ID: AA035384) and nephropathic cystinosis (CTNS, ID: W94331)." (PMID 16956415, 2006). "Firstly, since cysteamine treatment does not reverse Fanconi syndrome or inhibit ESRD, we hypothesized the presence of other confounding genes that could be affected in cystinosis other than CTNS." (PMID 40111391, 2025). "Here, we found that treatment with CTNS mRNA resulted in a mild increase in receptor expression, which might indicate an overall improvement of diverse cellular pathways impaired in cystinosis proximal tubules." (PMID 38016974, 2023). "This accumulation results in impairment of normal cellular functions that eventually leads to multi-organ dysfunction, as CTNS is expressed in all tissues in the human body; however, the pathogenesis of cystinosis is not limited to cystine accumulation and is yet to be fully elucidated." (PMID 36768921, 2023). "Cystinosis is a rare autosomal recessive lysosomal storage disorder, caused by bi-allelic pathogenic variants in the CTNS gene leading to the malfunctioning or absence of the cystine-proton cotransporter cystinosin." (PMID 35406807, 2022). "Cystinosis is a rare lysosomal-storage disease associated with accumulation of cystine in renal proximal tubule, mainly caused by mutations in cystine transporter CYSTINOSIN (CTNS)." (PMID 35309912, 2022). "This dramatic case report underlines that HSPC transplantation holds the potential for therapeutic benefits for cystinosis with the restoration of CTNS expression in tissues, a decrease in cystine crystal accumulation, and the improvement of polyuria and photophobia." (PMID 34943781, 2021). "Therefore, we performed a transcriptome analysis comparing CTNS+/+ and CTNS−/− ciPTECs in the intent of identifying biological processes that are altered in cystinosis." (PMID 34884638, 2021). "If the patient’s partner does not carry a mutation in the CTNS gene, the chances that the child will develop cystinosis are minimal." (PMID 34944047, 2021). "Besides CLCN5 (DD1) and OCRL (Lowe syndrome and Dent disease type 2) genes, they include LRP2 (DB/FOAR), CUBN, AMN (Imerslund–Gräsbeck syndrome), and CTNS (nephropathic cystinosis)." (PMID 31947599, 2020). "The diagnosis of nephropathic cystinosis is generally based on measuring leukocyte cystine level, demonstration of corneal cystine crystals by the slit lamp examination and confirmed by genetic analysis of the CTNS gene." (PMID 31672123, 2019). "Nephropathic cystinosis (MIM 219800) is a rare inherited metabolic disease characterized by an impaired transport of the amino acid cystine out of lysosomes due to reduced or absent function of the specific carrier cystinosin, which is encoded by CTNS gene." (PMID 31888107, 2019). "The frequency of cystinosis is 1 in 100,000–200,000 in the United States and Europe, but is much lower in Asia, including Japan because of the absence of the 57-kb Northern European founder deletion in the CTNS gene in Middle Eastern and East Asian people." (PMID 28950840, 2017).
cystinosis (continued). "We also show that CMA defects are independent of lysosomal overload, suggesting that the absence of CTNS expression causes the defective autophagic balance in cystinosis." (PMID 25586965, 2015). "Altogether, our data support the idea that CMA impairment in cystinosis is not caused by lysosomal overload and suggest that CTNS deficiency is the main cause of CMA impairment in this disorder." (PMID 25586965, 2015). "Similarly, infusion of bone marrow hematopoietic stem cells into CTNS knockout mice with nephropathic cystinosis can reverse pathologic cystine accumulation and ameliorate progressive renal dysfunction." (PMID 26089915, 2015). "In our study we examined the direct consequences of cystinosin deficiency on proximal tubular reabsorption machinery in human proximal tubular cells after down-regulation of the CTNS gene with specific siRNA and confirmed the results in proximal tubular cells derived from patients with cystinosis." (PMID 25811383, 2015). "However, a mechanistic link between cystinosis symptoms in patients and mutations in the CTNS gene is not fully established at the molecular level, hampering efforts to develop new treatments." (PMID 35977944, 2022). "Given the fact that cystinosis is an autosomal recessive disorder, the chances for the child to develop cystinosis are extremely small when the partner is confirmed not to be carrier of a CTNS mutation." (PMID 34944047, 2021). "Diagnosis of cystinosis is confirmed by measuring elevated white blood cell (WBC) cystine levels and molecular testing of the CTNS gene." (PMID 37219641, 2023). "Thus, the boy with phenotype of infantile cystinosis did not have mutations in the CTNS gene." (PMID 31672123, 2019). "A striking example of this is represented by cystinosis, a LSD resulting from defects in the lysosomal transporter of cystine, cystinosin (CTNS)." (PMID 25586965, 2015). "We further demonstrate that, in the absence of JIP4, increased ubiquitylation accelerates CTNS degradation and results in in vivo phenotypes that resemble cystinosis." (PMID 40661466, 2025). "Another notable finding of our study is the specific effect of antioxidant ATX on CTNS-/- RPTEC, which corrects the ATP6V0A1 levels, enhances autophagosomal turnover, improves cystinosis-induced mitochondrial dysfunction, and rescues mitochondrial membrane potential." (PMID 40111391, 2025). "Defects in this pathway have been reported to be altered in cystinotic human proximal tubule cells, but not in CTNS−/− iPSCs or mouse cystinosis fibroblasts." (PMID 41208577, 2025). "To study possible CMA defective mechanisms in CTNS-KO PTCs, and because previous studies from our laboratory suggested that the CMA receptor LAMP2A is mislocalized in cystinosis, we first analyzed the subcellular distribution of LAMP2A in wild type and CTNS-KO PTCs." (PMID 30774622, 2019). "However, the relevance of this to cystinosis was not appreciated until the human CTNS gene was identified as a potential homologue." (PMID 35011573, 2021). "Here we describe a patient with typical phenotype of infantile nephropathic cystinosis with elevated white blood cell (WBC) cystine levels, but initially without identified mutations in the CTNS gene by Restriction Fragment Length Polymorphism (RFLP) and Sanger sequencing of genomic DNA." (PMID 31672123, 2019). "Surprisingly, while both cystinosin and cystinosinLKG interacted with NHE3, rescue of the expression of CTNS, but not CTNS-LKG, was able to restore normal trafficking of NHE3 in cystinosis patient PTCs and improve sodium and albumin uptake in CTNS-deficient PTC lines." (PMID 39990449, 2025).